STAC3 (SH3 and cysteine rich domain 3)
Description:
Required for normal excitation-contraction coupling in skeletal muscle and for normal muscle contraction in response to membrane depolarization. Required for normal Ca(2+) release from the sarcplasmic reticulum, which ultimately leads to muscle contraction. Probably functions via its effects on muscle calcium channels. Increases CACNA1S channel activity, in addition to its role in enhancing the expression of CACNA1S at the cell membrane. Has a redundant role in promoting the expression of the calcium channel CACNA1S at the cell membrane (By similarity). Slows down the inactivation rate of the calcium channel CACNA1C.
Synonyms: MGC2793; CMYO13; CMYP13; MYPBB; NAM
Tractability: Antibody: UniProt places it where antibodies can reach, with medium confidence; its Gene Ontology location is reachable by antibodies, with medium confidence.
Gene: Protein-coding gene on chromosome 12 (57,243,453 to 57,251,188, reverse strand). Ensembl gene ENSG00000185482.
Subcellular location: Cytoplasm; Cell membrane, sarcolemma; Cell membrane, sarcolemma, T-tubule
Subcellular location (Human Protein Atlas): Nucleoplasm; Cytosol
Gene Ontology:
Molecular function: identical protein binding; protein binding; calcium channel regulator activity
Biological process: neuromuscular synaptic transmission; skeletal muscle contraction; positive regulation of protein localization to plasma membrane; positive regulation of voltage-gated calcium channel activity
Cellular component: cytosol; nucleoplasm; cytoplasm; cytoplasmic side of plasma membrane; voltage-gated calcium channel complex; sarcolemma; synapse; T-tubule
Genetic constraint (gnomAD): Loss-of-function variants: 30 observed, 51.1 expected, observed/expected ratio (o/e) 0.59, 90% interval 0.44 to 0.8. The upper end of that interval is the gene's LOEUF score, 0.8, which puts it in group 3 of 6, group 1 being the genes least tolerant of losing a copy. Missense variants: 419 observed, 490.89 expected, observed/expected ratio (o/e) 0.85, 90% interval 0.79 to 0.93. Synonymous variants: 144 observed, 168.04 expected, observed/expected ratio (o/e) 0.86, 90% interval 0.75 to 0.98.
Gene-disease validity (ClinGen):
ClinGen rates the evidence that STAC3 causes each of these diseases.
Bailey-Bloch congenital myopathy (autosomal recessive): Definitive. Bailey-Bloch congenital myopathy is a neuromuscular disorder characterized by weakness, arthrogryposis, kyphoscoliosis, short stature, cleft palate, ptosis and susceptibility to malignant hyperthermia during anesthesia.
Homologues: Orthologues: chimpanzee STAC3 (99% identical), macaque STAC3 (99% identical), rabbit STAC3 (97% identical), guinea pig STAC3 (96% identical), rat Stac3 (94% identical), mouse Stac3 (93% identical), tropical clawed frog stac3 (69% identical), zebrafish stac3 (60% identical). Paralogues in human: STAC (37% identical), STAC2 (37% identical).
Diseases named in the same sentence as STAC3 in open-access papers:
STAC3 is named in the same sentence as 23 diseases in open-access papers, as found by Europe PMC text mining. Sharing a sentence is not in itself a finding about the gene and the disease. The quoted sentences say what the papers report.
Native American myopathy (6 papers, 2017 to 2023). Native American myopathy (NAM) is a neuromuscular disorder characterized by weakness, arthrogryposis, kyphoscoliosis, short stature, cleft palate, ptosis and susceptibility to malignant hyperthermia during anesthesia. "STAC3 mutations have been linked to Native American Myopathy (NAM), a severe congenital myopathy resulting in muscle weakness and skeleton alteration." (PMID 36862731, 2023). "STAC3 is the target for mutations causing the rare neuromuscular disease Native American myopathy (NAM)." (PMID 34129875, 2021). "Stac3 was identified as a novel adaptor protein that is required for EC coupling in zebrafish skeletal muscle and a missense mutation in STAC3 is causal for the congenital Native American myopathy." (PMID 33123029, 2020). "The adaptor protein STAC3 is essential for skeletal muscle excitation-contraction (EC) coupling and a mutation in the STAC3 gene has been linked to a severe muscle disease, Native American myopathy (NAM)." (PMID 28112192, 2017).
congenital myopathy (5 papers, 2020 to 2025). "Mutations in Stac3 cause STAC3 disorder, a congenital myopathy characterized by muscle weakness." (PMID 40779452, 2025). "Disruption of the STAC3-CT interaction results in STAC3 disorder, a congenital myopathy leading to symptoms such as facial weakness, ptosis, hypotonia, scoliosis, cleft palate, and susceptibility to malignant hyperthermia." (PMID 40779452, 2025). "Meanwhile, the STAC3 W284S variant has been found in myopathy patients with non-Native American ethnicity and novel STAC3 variants were identified in patients presenting congenital myopathy symptoms and MHS; altogether constituting the category of STAC3-related congenital myopathies." (PMID 32222817, 2020).
Malignant hyperthermia (3 papers, 2023 to 2025). Malignant hyperthermia is characterized by a rapid increase in temperature to 39-42 degrees C. Malignant hyperthermia may occur in response to either inhalational anesthetics such as halothane, to muscle relaxants such as succinylcholine, or to exercise. "Malignant hyperthermia (MH) is a rare pharmacogenetic disorder triggered by volatile anesthetics and succinylcholine, most often linked to pathogenic variants in RYR1, CACNA1S, and STAC3." (PMID 41300733, 2025). "Our data show that the three genes currently associated with malignant hyperthermia (RYR1, CACNA1S and STAC3) are all misregulated in groups 1 and 3, but not group 2." (PMID 36282542, 2023).
STAC3 disorder (3 papers, 2021 to 2025). "The most common mutation associated with STAC3 disorder, W284S, similarly to the STAC3-NT fragment, results in a severely reduced EC coupling calcium release, without a corresponding decrease in CaV1.1 function." (PMID 40779452, 2025). "As STAC3 interacts with CaV1.1, one could expect corresponding mutations in Cav1.1 that would give rise to a phenotype similar to STAC3 disorder." (PMID 34129875, 2021).
arthrogryposis (1 paper, 2022). A rare, non-progressive congenital disorder characterized by multiple joint contractures which are present at birth. "For variants in genes critical to excitation-contraction coupling (CACNA1S, SCN4A, STAC3), oedema may present as early as 15–18 w, simultaneously accompanied by arthrogryposis." (PMID 36761691, 2022).
asthenospermia (1 paper, 2021). "Our results reveal that inhibition of STAC3 expression significantly impaired male fertility by inducing oligozoospermia and asthenospermia, and this impairment can be ascribed to androgen deficiency." (PMID 33409656, 2021). "From a functional standpoint, in vivo lentiviral vector–mediated suppression of STAC3 resulted in a significant decrease in testosterone production, and thereafter caused impairment of male fertility by inducing oligozoospermia and asthenospermia." (PMID 33409656, 2021). "Consequently, inhibition of STAC3 expression caused impaired male fertility by inducing oligozoospermia and asthenospermia." (PMID 33409656, 2021).
Headache (1 paper, 2023). Cephalgia, or pain sensed in various parts of the head, not confined to the area of distribution of any nerve. "Among the shared genes, four genes (NEU2, SLC44A4, and EHMT2 on chromosome 6, and STAC3 on chromosome 12) were associated with both migraine and headache." (PMID 36808568, 2023). "Among these shared genome-wide significant genes between migraine, headache, and glycemic traits, four (NEU2, SLC44A4, EHMT2, and STAC3) were common to both migraine and headache that overlapped more than one glycemic trait." (PMID 36808568, 2023).
infertile (1 paper, 2021). "A previous study using microarray analysis has identified STAC3 as one of the most significantly down-regulated genes in infertile male patients." (PMID 33409656, 2021). "Apparently, we could not rule out the possibility that the pathological changes within seminiferous tubules from infertility patients may be detrimental to STAC3 expression." (PMID 33409656, 2021).
migraine (1 paper, 2023). "STAC3 has recently been discovered as a risk gene for migraine and metabolic traits." (PMID 36808568, 2023).
muscular dystrophies (1 paper, 2023). "Congenital myopathies and muscular dystrophies yielded a comparable ‘solved’ rate of 53%, spanning 16 genes, including known variants in STAC3, RYR1 and COL6A2/3 in addition to 21 novel variants across 14 genes." (PMID 37516995, 2023).
oculogastrointestinal-neurodevelopmental syndrome (1 paper, 2022). "In three of these cases, the diagnosis was made via rapid genome sequencing with trio analysis: CAPN15-related oculogastrointestinal neurodevelopmental syndrome, TTN-related disorder, and STAC3-related myopathy." (PMID 36422100, 2022).
myopathy (10 papers, 2013 to 2024). A disease of the muscle in which the muscle fibers do not function properly. "Interestingly, the skeletal muscle of KO fish presented several modified proteins involved in Ca2+ signaling, such as Stac3, known to be mutated in a Native American myopathy." (PMID 39175772, 2024). "In addition, the CaV1.1 function in EC coupling is perturbed in Native American myopathy, arising from mutations in the CaV1.1-associated protein STAC3." (PMID 32222817, 2020). "STAC3 controls excitation and contraction coupling in murine skeletal muscles and is responsible for a congenital condition known as Native American myopathy." (PMID 36808568, 2023). "Recently, the adaptor protein SH3 and cysteine‐rich containing protein 3 (STAC3) has been identified as a myopathy disease gene and as an additional essential EC coupling component." (PMID 30071129, 2018). "Our data show that Stac3 is essential for development of functional skeletal muscle and viable mice, and that Stac3 mutant mouse is a novel mammalian model for myopathies." (PMID 23626854, 2013). "Whereas, at present, no β1a-associated diseases are known, mutations in STAC3 have recently been shown to cause a rare form of myopathy." (PMID 32222817, 2020).
malignant (3 papers, 2017 to 2025). "While RYR1 has previously been linked to autosomal dominant mutations, STAC3, which was formerly associated exclusively with Native American Myopathy/Bailey-Bloch Myopathy, congenital hypotonia, and susceptibility to malignant hyperthermia, is now newly associated with CM-KDS in this study." (PMID 39966651, 2025).
tumor (2 papers, 2022 to 2023). "For example, CTLA4, STAC3, TBC1D10C and TNFSF13B were found to show weaker correlation with KIR (Killer Cell Immunoglobulin-like Receptor) family genes in tumor condition." (PMID 37908350, 2023).
STAC3 also shares sentences with these, for which no sentence is quoted: neuromuscular disease (2 papers); Azoospermia (1); congenital fibrosis of the extraocular muscles (1); eosinophilia (1); oedema (1); ophthalmoplegia (1); pontocerebellar hypoplasia, type 1C (1); ptosis (1); Respiratory insufficiency (1).